CCL18 (C-C motif chemokine ligand 18)
Diseases named in the same sentence as CCL18 in open-access papers (continued):
Sharing a sentence is not in itself a finding about the gene and the disease.
cancer (continued). "For example, it has been demonstrated that glycans and the soluble ligand CCL18 on extracellular vesicles (EVs) derived from cells mediated the interaction between exosomes and cancer cells." (PMID 33224950, 2020). "As a secretory protein, CCL18 is not only involved in immune and inflammatory processes, but also is known to participate in cancer development." (PMID 32948745, 2020). "What is more, the CCL18 chemokine, the level of which is markedly increased in the ascites of advanced-stage patients, promotes cancer cell migration." (PMID 32456078, 2020). "TAM-derived CCL18 has been reported to promote cancer cell invasion by inducing the epithelial–mesenchymal transition (EMT)." (PMID 33424843, 2020). "Another example of reciprocal communication between cancer cells and TAMs is given by the pathway that involves GM-CSF (granulocyte-macrophage colony-stimulating factor) and CCL18 (C-C motif chemokine ligand 18)." (PMID 33143050, 2020). "The last part of the paper describes the possibility of using CCL18 as a therapeutic target during anti-cancer therapy." (PMID 33114763, 2020). "CCL18 also causes HUVECs EMT, which is dependent on ERK MAPK activation and the Akt/PKB→GSK-3β→Snail pathway, as well as EMT of cancer cells." (PMID 33114763, 2020). "Taken together these data strongly support that synergistic influence of VEGF and CCL-18 are critical for migratory/invasive responses of cancer cells to M2a macrophages." (PMID 31214501, 2019). "Although our study only confirms the clinical significance of serum CCL18 in patients with LSCC, CCL18 is also reported to be an efficient molecular target in TME to repress cancer progression." (PMID 31839826, 2019). "CCL18, a CC chemokine produced by M2 macrophages, is known to correlate with cancer initiation and progression." (PMID 30768878, 2019). "Since then, CCL-18 has been characterized as responsible for cancer progression in various cancer types." (PMID 31214501, 2019). "CCL18, as one of the most important cytokines secreted by M2 TAMs, functions critically in cancer metastasis." (PMID 30181713, 2018). "Significantly more naive CD4+ T cells adhered to all the cancer samples, even those with the least numbers of CCL18+ TAMs, compared to the DCIS samples." (PMID 28290464, 2017). "Paracrine loops of colony-stimulating factor-1 (CSF-1)/EGF and granulocyte-macrophage colony-stimulating factor (GM-CSF)/CCL18 between carcinoma cells and macrophages have been shown to lead to increased carcinoma cell invasion." (PMID 28143526, 2017). "Our findings demonstrate that elevated autocrine CCL18 accelerates cancer cell growth and invasion via Akt activation in OSCC." (PMID 26919103, 2016). "ELISA and tissue microarrays were used to assess CCL18 in ascites and phospho-Pyk2 expression in cancer tissues respectively." (PMID 27613122, 2016). "In this study, we demonstrate that elevated autocrine CCL18 facilitates cancer cell growth and invasion via Akt activation during the development of OSCC." (PMID 26919103, 2016). "Our findings provide new insights into the role of CCL18 in cancer and new therapeutic targets for future OSCC treatment." (PMID 26919103, 2016). "CCL18 released by breast TAMs promoted the invasiveness of cancer cells by triggering integrin clustering and enhancing their adherence to the extracellular matrix." (PMID 28053982, 2016). "CCL18 is a member of CCL chemokines and its expression has been associated with poor prognosis in some cancers." (PMID 27613122, 2016). "The data presented here indicate that elevated CCL18 promotes OSCC development by endowing cancer cells with a more malignant phenotype." (PMID 26919103, 2016). "Since CCL18 has been demonstrated to be released by TAMs which play important roles in malignant diseases, CCL18 has been increasingly considered to be involved in the pathogenesis and progress of various cancers." (PMID 25197632, 2014).
cancer (continued). "In PCa tissues, positive immunostainings of CCL18 were observed in the cytoplasm of macrophages and cancer cells." (PMID 25197632, 2014). "Urine samples were pooled, and whole cells or cell lysates of the cancer cell line pool and UROtsa cells were added to the urine sample and re-analyzed for CCL18 and A1AT using ELISA." (PMID 24011266, 2013). "CCL18 is thought to promote the invasiveness of cancer cells by triggering integrin clustering and enhancing their adherence to the extracellular matrix, and a receptor (PITPNM3) for this cytokine has been recently identified." (PMID 22629457, 2012). "In the current study, we demonstrate that hBD-3 can promote macrophage expression of IL-1α, IL-6, IL-8, and CCL18; i.e., cytokines and chemokines that are produced by TAMs as components of the cancer-related inflammation." (PMID 20544025, 2010). "Importantly, the study demonstrated that both TAM secreted CCL18 and cancer cell secreted GM-CSF are required for the maintenance of cancer cell mesenchymal/metastatic phenotype and macrophage tumor-promoting polarization." (PMID 39044824, 2024). "Conversely, in OC, CCL18 has been found to increase cancer cell proliferation." (PMID 38520216, 2024). "CCL18+ TAM subpopulation is also an important element in cancer immune evasion." (PMID 38347955, 2023). "By contrast, CCL18-PITPNM3 signaling in stromal cells might cause the explosive release of inflammatory cytokines, which will influence the characteristics of cancer cells." (PMID 36418470, 2023). "Besides, six factors had inverse causal associations with cancer, including CCL15, CCL18, CCL19, CCL20, CCL21, and CCL28." (PMID 38075694, 2023). "Indeed, CCL18 can bind to the PITPNM3 receptor of cancer cells to induce integrin clustering that enhances the invasion of the extracellular matrix by cancer cells leading to their migration and metastasis." (PMID 37143666, 2023). "CCL18 blockade might inhibit esophageal carcinogenesis by preventing TAMs recruitment and cancer cell proliferation." (PMID 36850011, 2023). "Furthermore, the pan-cancer analyses between CCL18 and immune checkpoints expression have important implications for cancer immunotherapy." (PMID 36850011, 2023). "In particular, the metastatic ecosystem was found to feature remarkable reprogramming of immunosuppressive cells such as FOXP3+ Treg cells, LAMP3+ tolerogenic DCs, CCL18+ M2‐like macrophages, RGS5+ cancer‐associated fibroblasts (CAFs), and LGALS1+ microglial cells." (PMID 36529697, 2023). "Excessive production of CCL18 by TAMs is correlated with increased aggressiveness of cancer cells." (PMID 37143666, 2023). "Therefore, CCL18 represents a promising therapeutic target for blocking GM-CSF-induced cancer metastasis." (PMID 35865534, 2022). "In summary, combined detection of CCL18 and CXCL1 chemokines, and C1D, TM4SF1, FXR1, and ZNF573 autoantibodies can improve the specificity and sensitivity of OC diagnosis, and its diagnostic efficiency is higher than that of other malignant tumors." (PMID 34995016, 2022). "The effect of CCL18 has been fairly well established in various cancer models." (PMID 35955670, 2022). "Many previous studies have confirmed that CCL18 plays an oncogenic role in a variety of cancers." (PMID 34354751, 2021). "Finally, CCL18 was involved in immune tolerance toward cancer to influence cancer cell activation and migration." (PMID 33679883, 2021). "In this context, another study demonstrated that CCL18 induced cell epithelial-mesenchymal transition and promoted cell migration and invasion, therefore it would be interesting to investigate factors that promote CCL18 expression in oral epithelia, and how CCL18 upregulation affects cancer cells." (PMID 34025655, 2021). "For this reason, understanding how CCL18 acts can be useful for anti-cancer therapy." (PMID 33114763, 2020). "CCL18 is mainly secreted by M2-TAMs and promotes cancer progression in a variety of human cancers." (PMID 33224886, 2020).
cancer (continued). "Hence, the aim of the present paper is to gather all the key information about the role of CCL18 in cancer." (PMID 33114763, 2020). "Therefore, CCL18 inhibits the action of some anti-cancer chemokines and, to a much lesser extent, pro-cancer ones." (PMID 33114763, 2020). "CCL18 is a potential therapeutic target for anti-cancer therapy." (PMID 33114763, 2020). "In particular, CCL18 promotes the EMT activation of blader cancer cells by activating CCR8." (PMID 33114763, 2020). "Therefore, cytokine CCL18 exert its function via influencing both cancer cells and their surrounding TME." (PMID 31839826, 2019). "On the other hand, CCL18 as a secreted cytokine also remodels TME to promote cancer progression." (PMID 31839826, 2019). "In glioblastoma, a distinct EV uptake mechanism was recently uncovered, which involves a triple interaction between the chemokine receptor CCR8 on cancer cells, glycans exposed on EVs and the soluble ligand CCL18 as a bridging molecule connecting EVs to cancer cells." (PMID 30925927, 2019). "For example, CCL18 represses the anti-cancer immune response by recruiting regulatory T (Treg) cells and induce an immune suppression environment that finally leads to suppress deleterious inflammation and cancer progression 32-35." (PMID 31839826, 2019). "We also found that CD163 could directly interact with CCL18 and CD86 which were associated with T-lymphocyte activation, indicating CD163 may be involved in cancer immunosurveillance." (PMID 29152078, 2017). "The role of CCL18 in cancer development also seems to vary among cancers." (PMID 26919103, 2016). "Chemokine (C-C motif) ligand 18 (CCL18) has been implicated in the pathogenesis and progression of various cancers; however, in oral squamous cell carcinoma (OSCC), the role of CCL18 is unknown." (PMID 26919103, 2016). "Therapies targeting PI3K/Akt signaling have demonstrated impressive anticancer activities against a broad range of human cancers; therefore, agents blocking CCL18-induced PI3K/Akt signaling might provide complementary effects in OSCC treatment." (PMID 26919103, 2016). "Chemokine (C-C motif) ligand 18 (CCL18), a member of the CC chemokine subset, plays a crucial role in immune processes and inflammation by triggering biological responses in dendritic cells, fibroblasts, monocytes/macrophages, and cancer cells." (PMID 26919103, 2016). "Aberrant expression of the chemokine CCL18 has been associated with several types of cancers, whereas its role in OSCC progression has not been studied." (PMID 26919103, 2016). "Moreover, CCL18 contributes to cancer cell growth and invasion in an autocrine manner via Akt activation during OSCC progression." (PMID 26919103, 2016). "Such complexes may be functionally relevant as CCL18 is both constitutively and inducibly expressed to the high levels in various tissues normally and in disease conditions, such as cancer and inflammation." (PMID 25636406, 2015). "CC chemokine ligand 18 (CCL18) promotes malignant behaviors of various human cancer types." (PMID 25197632, 2014). "Besides these, CCL18 has been demonstrated to promote the invasiveness of cancer cells by triggering integrin clustering and enhancing their adherence to the extracellular matrix (ECM)." (PMID 25197632, 2014). "Upper results implied that CCL18 can prolong the survival time of cancer cells." (PMID 25197632, 2014). "In addition, as previous reports suggested, the production of CCL18 is correlated with the severities of several malignant tumors, and one of the potential producers of CCL18 is CD163+ macrophages." (PMID 24489574, 2013). "Because CCL18 is a chemokine, which might also be involved in the homing of cancer cells, we also investigated the chemotacic properties of CCL18 on A549 cells." (PMID 23349697, 2013). "Furthermore, DTX with RS significantly decreased the production of CCL22 and CCL18, which was previously reported to correlate with the severity and prognosis in cancer patients." (PMID 24489574, 2013).
cancer (continued). "Furthermore, DTX with RS significantly decreased the production of CCL18, which was previously reported to correlate with the severity and prognosis in cancer patients." (PMID 24489574, 2013). "Studies have shown that cancer cells after EMT can secrete GM-CSF to activate macrophages to the TAMs phenotype, while activated macrophages induce EMT of cancer cells by secreting CCL18, this positive feedback loop is associated with metastasis of breast cancer cells." (PMID 40131539, 2025). "Thus, CCL18 should be a potential therapeutic target for anti-cancer therapy." (PMID 38347955, 2023). "Furthermore, several immunosuppressive cells were identified to reprogram the metastatic ecosystem, including FOXP3+ regulatory T (Treg) cells, LAMP3+ tolerogenic DCs (tDCs), CCL18+ M2‐like macrophages, RGS5+ cancer‐associated fibroblasts, and LGALS1+ microglial cells." (PMID 36529697, 2023). "Although the abundance of cytokines, such as CCL18 and IL1b, in cancer cells may be responsible for initiating NF-kB signaling through activation of IKK in the CAF subset, numerous feedback loops in the TME lead to the failure of therapeutic strategies to target inflammatory factors." (PMID 35189958, 2022). "However, in most kind of cancers, CCL18 acted as a promoter." (PMID 35609322, 2022). "Similarly, CCL18 derived from TAMs induces cancer cell EMT to form a positive feedback loop." (PMID 33224886, 2020). "CCL18 may have an influence on the proliferation of cancer cells." (PMID 33114763, 2020). "However, CCL18 may also reduce cancer cell migration by activating GPER1/GPR30, where this chemokine interferes with the action of CXCR4 on pre-B acute lymphotic leukemia cells." (PMID 33114763, 2020). "Hence, CCL18 shows the potential of being a crucial regulator in cancer progression and metastasis." (PMID 30216450, 2019). "However, we have to mention that CCL18 neutralizing antibody only partially inhibits the function of M2-like TAMs, which means that other mechanisms are also involved in mutual communication between TAMs and cancer cells." (PMID 30181713, 2018). "Hence, in fibrotic diseases as well as in various cancers CCL18 levels are increased." (PMID 28957436, 2017). "These interaction network analyses reinforce the distinct and complex roles of CCL18 and EGF in cancer biology, particularly in BRCA." (PMID 40692603, 2025). "These gene sets likely reflect molecular partners or pathways modulated by CCL18 and EGF, encompassing processes such as immune regulation, extracellular matrix remodeling, and cell migration—hallmarks of cancer progression." (PMID 40692603, 2025). "CCL18, primarily secreted by TAMs, activates NF-κB through PITPNM3, enhancing EMT gene expression and promoting cancer cell migration and metastasis." (PMID 40361472, 2025). "To investigate the expression profiles of CCL18 and EGF across multiple cancer types, we performed a comprehensive differential expression analysis using data from TCGA." (PMID 40692603, 2025). "Seven chemokines (CCL18, CCL8, CXCL9, CXCL10, CXCL11, CCL26, and CCL7) showed positive relations in more than 25 cancer types." (PMID 38655053, 2024). "MIP-4, also known as CCL18, is a secreted protein involved in several biological processes, including immune response, inflammation, and cancer development." (PMID 39132322, 2024). "Treatment with an anti-CCL18 antibody, or TAM/MDM transfection with CCL18-siRNAs abrogated cancer cell invasive and migratory capacities." (PMID 39044824, 2024). "Pep3 is, to our knowledge, the first peptide to inhibit CCL18 and greatly reduce the ESCC cancer progression." (PMID 36850011, 2023). "Differentiated M2-like TAMs are known to secrete pro-tumoral cytokines, such as CCL18, TNF-α, and matrix metalloproteinases, that can promote cancer progression." (PMID 36674955, 2023).
cancer (continued). "There are 28 types of chemokines (CCL1-CCL28) belonging to the CC chemokine subfamily, among which CCL2, CCL3, CCL5, CCL15, CCL18 and CCL26 exert some regulatory effects on pathological processes such as TAMs infiltration and polarization in cancer." (PMID 36173487, 2023). "M2 macrophages secrete anti-inflammatory cytokines such as IL-10, CCL18, and CCL22, which are beneficial to cancer cell growth." (PMID 37758759, 2023). "Knockdown of miR-484 and overexpression of CCL-18 both promoted the phosphorylation of PI3K and AKT in MGC-803 cell, suggesting that miR-484 exerts anti-cancer effects by targeting the CCL-18-PI3K/AKT pathway." (PMID 35356223, 2022). "CCL18 facilitated cancer development by upregulating HOTAIR expression, providing a potential new therapeutic target for cancer diagnosis and treatment." (PMID 35222443, 2022). "Cell free ascitic fluid containing CCL18 induced the migration of CaOV3 and OVCAR3 cancer cell lines in vitro in a dose-dependent manner." (PMID 35682890, 2022). "Many macrophages-derived cytokines present in the TME have already been verified to affect the response of cancer cells to chemotherapy like CCL2, CCL22, IL-6 and CCL18." (PMID 36151545, 2022). "CCL18 in turn increases the expression of EMT promoting transcription factors in a positive feedback loop to further promote migration and invasion of cancer cells to distant sites." (PMID 35865534, 2022). "Meanwhile, M2 macrophages can produce various matrix metalloproteinases (MMPs) and chemokines, such as MMP-2, MMP-7, MMP-9, CCL18, and CCL22, which promote the metastasis of cancer cells." (PMID 36685978, 2022). "Various factors secreted from CAFs or TAMs, such as TGF-β, SDF-1, and CCL18, induce EMT, invasiveness, migration, and stemness in cancer cells, as reported by studies that used conditioned medium stimulation or indirect co-culture in Transwells." (PMID 34885065, 2021). "CC chemokine ligand 18 (CCL18) is a CC chemokine constitutively highly expressed in human lung and plasma and upregulated during inflammatory and cancer processes in many organs." (PMID 33918621, 2021). "Other genes overexpressed in Cluster 1 were chemokine and cytokine related genes (CCL15, CCL18, TNF, IL11RA, XCR1), the immune checkpoint protein PD-1 (PDCD1), and cancer-related genes (SSX1 and MAGEA4)." (PMID 33298930, 2020). "The main factors affecting the biological activity of cancer cells are IL-10, IL-6, TGF-β, VEGF, CCL18, CCL22, and microRNA." (PMID 32456078, 2020). "It includes a description of the signal transduction from PITPNM3 in CCL18-dependent migration, invasion, and epithelial-to-mesenchymal transition (EMT) cancer cells." (PMID 33114763, 2020). "Taken together, our study suggests that M2 TAMs produce CCL18 to induce EMT and cancer stemness, which in turn leads to SCCHN metastasis." (PMID 30181713, 2018). "Reciprocally, as a major component of solid tumors, TAMs promote cancer cell invasion and metastasis by secreting various cytokines, for example, TGF-β, NF-κB, VEGF, and CCL18." (PMID 28955335, 2017). "CD68+ cells were located in the cancer stroma, while there was little co-localization of CD68+ and CCL18+ staining in OSCC tissues." (PMID 26919103, 2016). "Thus, CCL18 could act in an autocrine manner, paracrine manner, or both, during cancer development." (PMID 26919103, 2016). "In fact, the synergistic expression of CCL18 and VEGF by the TAMs promoted endothelial cell migration and angiogenesis in this type of cancer." (PMID 28053982, 2016). "In vitro and in vivo studies show that macrophages enhance cancer cell invasion and migration by releasing cytokines and chemokines regulated by EGF and CCL18 or by remodeling the extracellular matrix through protease activity, increasing chemoattractant availability." (PMID 40692603, 2025).